ARG1 (arginase 1)
Diseases named in the same sentence as ARG1 in open-access papers (continued):
Sharing a sentence is not in itself a finding about the gene and the disease.
bladder cancer (5 papers, 2021 to 2025). "Additionally, ILC2 numbers have been shown to correlate with infiltrating MDSCs in recurrent bladder cancer, where ILC2-derived IL-13 upregulated the expression of T cell-suppressing genes including ARG1 (encoding arginase-I; ARG1) and NOS2 (encoding inducible nitric oxide synthase; iNOS)." (PMID 33401460, 2021). "In this study, PEGylated recombinant human arginase 1 (BCT-100) was shown to sharply deplete the levels of intracellular and intratumoral arginine and display an antiproliferative effect on tumor growth in bladder cancer cells." (PMID 33791071, 2021).
co-infection (5 papers, 2009 to 2025). "Enhanced chronic inflammation driven by M. tuberculosis and HIV co-infection may promote Arg-1–expressing MDSCs at the site of infection thereby advancing TB disease progression." (PMID 35092727, 2022). "Quantification of co-expression revealed a significantly elevated expression of Arg-1+ (P = 0.006), Arg-1+MAC387+ (P = 0.002), Arg-1+CD15+ double-positive (P = 0.05), and Arg-1+CD15+MAC387+ triple-positive (P = 0.03) cells in TB/HIV co-infection compared with TB infection." (PMID 35092727, 2022).
cryptococcal infection (5 papers, 2019 to 2024). "Our data show that LangDC1 modulate an early cytokine immune response and arginase-1/iNOS expression in the lung, promoting an environment susceptible to cryptococcal infection." (PMID 36012781, 2022). "And targeted inhibition of arginase-1 in MDSCs protects against Cryptococcus neoformans infection." (PMID 38566195, 2024). "Notably, pharmacological inhibition of arginase-1 expression by a specific inhibitor of p38, SB202190, or an orally available receptor tyrosine kinase inhibitor, vandetanib, significantly enhances T-cell mediated antifungal responses against cryptococcosis." (PMID 35835754, 2022). "Interestingly, the conditional knockout of Arg1 in IM and the deletion of STAT6, a transcriptional regulator of Arg1, in hematopoietic cells could not reverse the impact of IM on host outcomes during acute cryptococcosis." (PMID 30897162, 2019).
cyst (5 papers, 2016 to 2026). A sac-like closed membranous structure that may be empty or contain fluid or amorphous material. "These M2 macrophages, characterized by high arginase 1 (ARG1) expression, promote cyst enlargement in Pkd1−/− mice, suggesting ARG1 as a potential therapeutic target." (PMID 41431718, 2026). "Supporting this, animal models and patient samples have demonstrated upregulation of M2 macrophage‐related genes (Arg1, Ym1) and cytokines (IL‐10, TGF‐β) at lesion sites, with their mRNA levels positively correlated with cyst diameter and growth rate." (PMID 40921168, 2025).
endometriosis (5 papers, 2022 to 2024). The growth of functional endometrial tissue in anatomic sites outside the uterine body. "ROC analysis of the sensitivity and specificity was performed to evaluate the potential of serum Arg-1 concentration and arginase activity as diagnostic indicators of endometriosis." (PMID 38592313, 2024). "In addition to the real-time PCR data, we also showed a significant increase (p-value<0.05) in the production of the protein encoded by the ARG1 gene, arginase 1, in the endometriosis foci compared to the uterus (S.3)." (PMID 39253270, 2024). "As in OvCa, we assume that elevated levels and activity of Arg-1 and/or Arg-1 may be present in the sera of endometriosis patients and may have diagnostic or prognostic potential." (PMID 38592313, 2024). "Furthermore, we have shown that the diagnostic value of Arg-1 serum concentration was even higher in differentiating patients with endometriosis from healthy, asymptomatic women (ROC AUC = 0.912, lower limit of the 95% confidence interval = 0.859 for groups B and K2)." (PMID 38592313, 2024). "The absence of determined standards and reference ranges, both in the course of endometriosis and in relation to other diseases, may indeed partially or completely hinder the potential diagnostic value of determining the concentration of Arg-1/arginase activity for the diagnosis of endometriosis." (PMID 38592313, 2024). "The analysis of M2 marker gene expression revealed significant differences in the expression levels of ARG1 (p-value <0.05), with a predominant presence in the endometriosis foci." (PMID 39253270, 2024). "For example, miR-301a-3p overexpression in vitro, as well as in vivo experiments involving endometriosis-derived EVs administration, significantly increased ARG1 expression in macrophages." (PMID 35563789, 2022). "Moreover, a significant decrease in serum Arg-1 levels after surgery was also observed in the non-endometriosis control group." (PMID 38592313, 2024). "We have shown that the determination of Arg-1 concentration could be considered a promising test for differentiating patients with endometriosis from patients with other gynaecological disorders (ROC AUC = 0.848 for groups GB and K1)." (PMID 38592313, 2024). "The detected elevated levels of serum Arg-1 may indeed indicate its involvement in immunosuppressive and pathomechanisms of endometriosis." (PMID 38592313, 2024). "Thus, we were able to show that the expression of the M1 macrophage marker genes TNF and IL12B was significantly decreased in the endometriosis foci, and the expression of the M2 macrophage marker gene ARG1 was significantly increased." (PMID 39253270, 2024). "Inhibition of the enzymatic activity of Arg-1 might impede the progression of endometriosis and represent a targeted and tailored approach, offering new possibilities for managing this complex gynaecological condition." (PMID 38592313, 2024). "Furthermore, it was observed that in the K2 group of healthy women, Arg-1 concentration was significantly lower than in the K1 group of women operated for reasons other than endometriosis." (PMID 38592313, 2024). "Additionally, a decrease in the production of the M2 macrophage marker Arginase 1 was found in the endometriosis foci after therapy compared to the control group (p-value<0.05)." (PMID 39253270, 2024). "As a result, ARG1+ macrophages may suppress T cell activation in a similar manner in endometriosis to that in tumors, affecting the immunological response and deriving inflammation in the pro-endometriotic niche." (PMID 35563789, 2022). "The use of Arg-1 concentration determination as a diagnostic test could have a practical supportive value in women with clinical suspicion of endometriosis but without clear imaging features (such as endometrial cysts)." (PMID 38592313, 2024).
endometriosis (continued). "Therefore, it should be considered that these pathologies may significantly and to an undetermined extent disturb the reliability of serum Arg-1 concentrations and arginase activity assessments for endometriosis diagnosis." (PMID 38592313, 2024). "Therefore, we hypothesise that a similar immunosuppressive mechanism mediated by Arg-1, as described in OvCa, may play a role in endometriosis." (PMID 38592313, 2024). "Under the condition of endometriosis, the up-regulation of the exosomal miR-301a-3p significantly enhanced the ability of exosomes to induce macrophage M2 transformation, promoted the expression of arginase-1 (ARG-1) and PI3K, and inhibited the expression of PTEN." (PMID 36548867, 2022). "So far, there are no publications about the role of arginase 1 in the endometriosis diagnosis." (PMID 38592313, 2024). "However, in contrast to OvCa-derived EVs that have already been demonstrated to carry ARG1, so far, no studies have confirmed the presence of ARG1 in the cargo of endometriosis-derived EVs." (PMID 35563789, 2022). "Although no changes in cell uptake were detected, sEVs from endometriosis induced a polarization of macrophages toward an M2 phenotype, characterized by lower IL1B and TNF expression and a tendency to increase MRC1 and ARG1 levels." (PMID 39062452, 2024).
endotoxemia (5 papers, 2012 to 2023). "Arginase-1-deficient mice as compared with control mice exhibited higher plasma arginine concentration concomitant with enhanced NO production in endothelial cells and jejunal tissue during endotoxemia." (PMID 24465919, 2014). "Our study demonstrates that arginase-1 deficiency in murine endothelial cells and macrophages resulted in an increased plasma L-arginine concentration and an enhanced NO production during prolonged in vivo exposure to endotoxemia." (PMID 24465919, 2014). "If the host is infected with Schistosoma mansoni, Arg1 can effectively suppress Th2-mediated fibrosis, Th1/Th17-mediated intestinal damage, iNOS production, and endotoxemia." (PMID 37692380, 2023). "Up-regulation of Ym-1 and Arginase-1 was observed in peritoneal macrophages collected 90 minutes post chtx administration in mice with ongoing endotoxemia." (PMID 22654663, 2012). "It is conceivable that Arg1 induction in multiple cell types modulates HPV during endotoxemia." (PMID 31159807, 2019). "Reduced arginase-1 activity in Arg1fl/fl/Tie2-Cretg/− mice resulted in increased inflammatory response and NO production by NOS2, accompanied by a depressed microcirculatory flow during endotoxemia." (PMID 24465919, 2014). "Furthermore, we showed that, in the absence of arginase-1 in endothelial cells or macrophages, only NOS2-derived NO production significantly increased during endotoxemia, whereas NOS3-derived NO production did not benefit from the arginase-1 deficiency." (PMID 34769369, 2021).
experimental autoimmune encephalomyelitis (5 papers, 2019 to 2023). An autoimmune demyelinating disease of the central nervous system that is produced experimentally in animals by the injection of homogenized brain or spinal cord in Freund's adjuvant. "Arg-1 is expressed exclusively in infiltrating myeloid cells but not microglial cells in models of spinal cord injury and experimental autoimmune encephalomyelitis (EAE)." (PMID 36761741, 2023). "For example, Arg-1 was detected in both macrophage and reactive astrocytes after SCI, whereas iNOS was expressed in microglial cells, astrocytes, and neurons, especially in experimental autoimmune encephalomyelitis models." (PMID 33192269, 2020). "In an experimental autoimmune encephalomyelitis, elevated PD-L1 expression mediated the protective effects of MDSCs, whereas no Arg-1 or NO was detected in G-MDSCs22." (PMID 31011190, 2019).
hematoma (5 papers, 2016 to 2023). A hematoma is a collection of blood from a vascular structure into an extravascular space. "Arginase-1 expression was mainly detected in CX3CR1+ macrophages/microglia in the peri-hematoma region (arrows), suggesting that macrophages/microglia in the injured brain are polarized to the M2 phenotype." (PMID 27094968, 2016). "We observed a significant increase in IL-10, TGF-β, and Arg1 (M2 markers) on day 3, and the levels reduced from day 7 until day 28 on the hematoma side, and no significant changes were detected on the other side." (PMID 37190062, 2023).
inflammatory bowel disease (5 papers, 2020 to 2025). A spectrum of small and large bowel inflammatory diseases of unknown etiology. "ToxoROP16I/III promotes the polarization of M2 cells, and enhances the synthesis of Arg-1, IL-10, transforming growth factor-β1, and IL-13, which may ameliorate the pathogenesis of inflammatory bowel disease in an in vitro experimental model." (PMID 35911679, 2022).
Lewis lung carcinoma (5 papers, 2017 to 2026). "In a mouse model of Lewis lung carcinoma, myeloid cells express high levels of Arg1, resulting in impaired T cell function." (PMID 36727849, 2023).
prostate carcinoma (5 papers, 2010 to 2023). A carcinoma that arises from epithelial cells of the prostate gland. "A study on prostate cancer indicated that ARG1 and IDO alter intratumoral CD8+ T cells’ functions in plasmacytoid DCs simultaneously." (PMID 33679700, 2020). "NO-mediated immunosuppression has been demonstrated in human prostate carcinoma by its inhibition of arginase 1 (ARG1) in T cells and diminished antitumoural activity of tumour-infiltrating lymphocytes (TILs) resulting from tyrosine nitration." (PMID 33321789, 2020). "In vivo studies of prostate cancer demonstrated that M2 TAMs which express arginase-1 and COX-2 are recruited to these hypoxic centers after irradiation and promote tumor growth." (PMID 30828330, 2019).
retinal ischemia (5 papers, 2020 to 2025). A ischemic disease that involves the retina. "Arginase-1 is found in the cytoplasm and has been shown in retinal ischemia/reperfusion (I/R) and oxygen-induced retinopathy (OIR) models in mice to protect against neurovascular degeneration and to limit vitreoretinal neovascularization." (PMID 40076703, 2025). "Arg1 has been reported to play a protective role in retinal ischemia–reperfusion injury by inhibiting macrophage inflammation and OS." (PMID 36826575, 2023). "Two isoforms of arginase enzymes (Arg-1 and, in a major proportion, Arg-2) are expressed in the retina, whose regulation could be crucial in the development of some retinopathies such as DR or retinal ischemia." (PMID 32961933, 2020).
tuberculosis (5 papers, 2016 to 2022). A chronic, recurrent infection caused by the bacterium Mycobacterium tuberculosis. "Overexpression of IL-10 by macrophages and monocytes (under control of the CD68 promoter) was shown to induce the expression of Arg1 and other markers associated with alternative macrophage activation during M. tuberculosis infection, increasing host susceptibility to TB." (PMID 27849167, 2016). "tuberculosis-infected MiR-21−/− bone marrow derived macrophages (BMDMs) showed increased levels of pro-inflammatory mediators including nitric oxide synthase 2 (Nos2) mRNA, arginase 1 (Arg1), and ROS with concomitant containment of M. tuberculosis." (PMID 34248974, 2021). "Poorly formed necrotic TB granulomas with a high expression of M. tuberculosis antigens were elevated in TB/HIV–co-infected lymph nodes, and inducible nitric oxide synthase and Arg-1 expression was significantly higher in TB/HIV–co-infected compared with HIV-negative TB or control tissues." (PMID 35092727, 2022).
airway hyperresponsiveness (4 papers, 2011 to 2025). "In addition, research has shown that upregulation of Arg1 expression results in an increase in polyamine synthesis, ultimately leading to the development of airway hyperresponsiveness, which may be partially attributed to the inhibiting effect of Arg1 overexpression on NO synthesis." (PMID 38049863, 2023).
Allergy (4 papers, 2013 to 2025). An allergy is an immune response or reaction to substances that are usually not harmful. "During the challenge phase of allergy, lung macrophages upregulate arginase-1 expression, inducing an immunosuppressive response to limit the lung DC function and antigen-specific antibody production." (PMID 39806495, 2025). "During the challenge phase of allergy, AMs upregulate YM1 and Arg1 expression, inducing an immunosuppressive response to limit the lung DC function and antigen-specific antibody production." (PMID 38016013, 2024).
Autoimmunity (4 papers, 2021 to 2026). The occurrence of an immune reaction against the organism's own cells or tissues. "Firstly, the released cytokines from MDSCs play a pro-inflammatory and pathogenic role in autoimmunity, including Arg-1, NO, ROS, IFN-γ, and IL-1β." (PMID 37733169, 2024). "Immune modulation via ARG1-polyamine crosstalk regulates T cell differentiation, macrophage polarization, and microbiota interactions, influencing infection and autoimmunity." (PMID 41939876, 2026). "Regulatory T cells (Tregs): Tregs are essential for the prevention of autoimmunity and have a suppressive effect on effector T cells.MDSCs: MDSCs inhibit specific and nonspecific T-cell responses by producing large amounts of nitric oxide, arginase-1, and immunosuppressive cytokines, such as IL-10." (PMID 40672947, 2025). "Some molecules from MDSCs (Arg-1, PGE2, miR-29a-3p, and miR-93-5p) have been reported to inhibit T cell responses and promote IL-10+ Breg cell generation in autoimmunity, consistent with MDSC suppressive activity." (PMID 37733169, 2024).
brain infarction (4 papers, 2016 to 2024). Tissue necrosis in any area of the brain, including the cerebral hemispheres, the cerebellum, and the brain stem. "Future studies will address how changes in both the NLR, as well as the factors that mediate the NLR, including ARG1, contribute to the evolution of brain infarct over time after AIS." (PMID 26515089, 2016).
brain injury (4 papers, 2015 to 2024). Acute and chronic (see also brain INJURIES, CHRONIC) injuries to the brain, including the cerebral hemispheres, CEREBELLUM, and brain STEM. "Pharmacological inhibition of PDE4B by 0.3 ​mg/kg A33 i.p. administered 30 ​min after traumatic brain injury induction, induced anti-inflammatory markers (e.g., Arginase-1) in phagocytes and limited lesion size." (PMID 38760316, 2024). "Regulation of Arg1 expression on microglia/macrophages at the right time may be a potential target for the treatment of ischemic brain injury." (PMID 36361836, 2022). "Interestingly, work from the laboratory of Christine Hsieh suggests that even if unique populations of Arg1+ macrophages are sorted after traumatic brain injury, a mixed phenotype is still observed." (PMID 26538310, 2015).
brain tumor (4 papers, 2021 to 2025). "In this study, treatment with the STAT6 inhibitor AS1517499 was associated with a significant decrease in Arg1 expression in microglia and a significant reduction in brain tumour burden." (PMID 35359423, 2022). "We used immunofluorescence (IF) to detect the levels of Ki67, CD31, and Arg-1 in LLC brain tumor tissues." (PMID 40687724, 2025). "We further examined the expression of Ki67, CD31, and Arg-1 in LLC brain tumor tissues using immunofluorescence (IF)." (PMID 40687724, 2025).
cutaneous leishmaniasis (4 papers, 2012 to 2022). Leishmaniasis affecting the skin. "This explains why the ARG1-dependent effect in cutaneous leishmaniasis was only observed at later time points of the infection." (PMID 34359992, 2021). "Here we show that L. donovani induces host arg1 expression through a mechanism that involves parasite-induced STAT6 activation, but different from the prevailing paradigm of alternative activation in cutaneous leishmaniasis, occurs even in the absence of a polarized type 2 cytokine response." (PMID 22275864, 2012).
diabetic nephropathy (4 papers, 2019 to 2024). "Additionally, fewer M2 macrophages (CD68+/Arg-1+) were found in the tissues from patients with diabetic nephropathy." (PMID 35280997, 2022). "In this study, we found that the administration of human umbilical cord blood-derived MSCs prevents the progression of diabetic nephropathy by inducing arginase-1 (Arg1), a key M2 marker that inhibits M1 polarization, in macrophages to improve mitochondrial biogenesis and function in TECs." (PMID 31285429, 2019).
emphysema (4 papers, 2019 to 2024). "On this note nILC2s have recently been shown to constitutively express arginase-1 (Arg-1), and the selective absence of this gene within ILC2s resulted in an exacerbated emphysema in response to Nb infection." (PMID 31019505, 2019).
endometrial cancer (4 papers, 2014 to 2025). Primary or metastatic malignant neoplasm involving the endometrium (mucous membrane that lines the endometrial cavity). "The gene ARG1 was upregulated at 5 weeks after fractionated therapy in 9 out of the 10 endometrial cancer patients (fold of change ranging from 0.7 for patient E4 up to 4.5-fold increase in expression for patient E6)." (PMID 28443095, 2017). "In addition, we noted a highly significant increase in arginase-1 activity in endometrial carcinomas compared with normal endometria, which was not the case for uterine sarcomas." (PMID 24658839, 2014).